AFP (alpha fetoprotein)
Diseases named in the same sentence as AFP in open-access papers (continued):
Sharing a sentence is not in itself a finding about the gene and the disease.
hepatitis B (continued). "Further statistical analyses showed that patients with hepatitis B and a high alpha-fetoprotein (AFP) level in serum (>200 ng/mL) showed a higher efficacy from Lenvatinib compared to Sorafenib." (PMID 36011021, 2022). "A total of 10.9% (15/138) of the patients were admitted with chronic infection of HBV, and 2.2% (3/138) of the patients were admitted with a family history of hepatitis B. The alpha-fetoprotein (AFP) serum-positive rate was 39.1% (54/138)." (PMID 35197961, 2022). "Cox regression analysis showed that hepatitis B (P = .023), AFP (P = .025), microvascular invasion (P = .010), and ALT (P = .009) were independent predictive values for disease-free survival." (PMID 35049245, 2021). "AFP is more sensitive in HCC (especially hepatitis B-related HCC), but it must be combined with imaging because it is a non-specific tumor marker." (PMID 35071004, 2021). "On the other hand, our data strongly suggest that AFP is a good test for the detection of HCC in patients with hepatitis B with an ALT level ≤ 2 ULN." (PMID 33490235, 2020). "The second study reported a 40-year-old man who was admitted to the hospital because of the presence of a liver tumor based on physical examination with hepatitis B. Laboratory examination showed that AFP was 4539.2 ng/ml." (PMID 32967689, 2020). "The first study reported a 62-year-old woman who was admitted to the hospital because of right upper abdominal drop pain with hepatitis B. Laboratory examination showed that AFP was 394.90 ng/ml (0–7 ng/ml)." (PMID 32967689, 2020). "The present study assessed the predictive value of AFP in the prognosis of hepatitis B-related acute-on-chronic liver failure because these patients always exhibited bad progress, and the short-term mortality is dramatically high." (PMID 29854714, 2018). "Half of the patients with PHSC were detected incidentally in their routine physical examinations for the hepatitis B. The elevation of alpha-fetoprotein (AFP) was found in 50% (five of 10) of the patients and 57.1% (four of seven) of the S-HCC patients." (PMID 30314525, 2018). "In summary, AFP is an indicator of the prognosis of hepatitis B-related acute-on-chronic liver failure." (PMID 29854714, 2018). "Dialysis patients exhibited higher rates of dual viral hepatitis B and C, lower serum alpha-fetoprotein levels, poorer performance status and greater model for end-stage liver disease scores than non-dialysis patients or matched controls (P < 0.05)." (PMID 29069858, 2017). "In patients with hepatitis B or C virus infection, measurements of serum AFP levels were suboptimal in detecting HCC as the AFP levels were frequently elevated even in the absence of HCC in patients with chronic hepatitis B or C." (PMID 27304617, 2016). "Because there is a large population of patients with hepatitis B or C virus infection in China, serum levels of AFP are measured routinely during health checkups to screen for HCC." (PMID 25886790, 2015). "HCC is usually associated with viral infections, such as hepatitis C and hepatitis B. HCC diagnosis is generally based on ultrasound scanning and serum alpha-fetoprotein (AFP) estimation every 6 months." (PMID 26487969, 2015). "In contrast, a Chinese research group identified CXCL1 together with thrombin light chain and alpha-fetoprotein as serological biomarkers for HCC in hepatitis B infected patients." (PMID 24260493, 2013). "The patient was under surveillance due to hepatitis B and had been subjected to AFP measurement and US scan 2, 8 and 14 months prior to his admission (AFP: 65, 69 and 60 ng/ml respectively)." (PMID 16042808, 2005). "All the patients were Child-pugh A; median alpha fetoprotein (AFP) level was 489.8ng/ml; 14(42.4%) patients were complicated with macrovascular invasion; and distant metastasis emerged in 27(81.8%) patients; 21(63.6%) patients were hepatitis B infection." (PMID 40082982, 2025).
hepatitis B (continued). "The elevated AFP may have resulted from active hepatitis B virus infection despite undetectable HBV DNA, or from tumor rupture." (PMID 41293148, 2025). "Additionally, hepatitis B or C infections, as well as serum concentrations of tumor markers—namely alpha-fetoprotein (AFP) and protein induced by vitamin K absence or antagonist-II (PIVKA-II)—should be taken into account when assessing prognostic factors." (PMID 38482199, 2024). "Furthermore, hepatitis B (P = .013), AFP (P = .045), microvascular (P = .024) and macrovascular (P = .029) invasions, BCLC stage (P = .016), and ALT (P = .026) were significant predictors for disease-free survival in univariate analyses." (PMID 35049245, 2021). "Moreover, CDCA8 levels were found to be independent of age (p = 0.682), gender (p = 0.43), α‐fetoprotein (AFP) serum levels (p = 0.516), liver fibrosis (p = 0.29) and hepatitis B (p = 0.317)." (PMID 34741389, 2021). "There was no statistical difference between the two groups with respect to clinical data (age, sex, hepatitis B history, preoperative liver function, and pre-operative AFP level) and disease examination-related data (number of lesions, maximum diameter of lesions, and expression of Ki67)." (PMID 33718156, 2021). "In terms of these univariable results, MPVI or EHS or both, AFP < 200 ng/mL, disease site, hepatitis B aetiology, and receipt of a previous procedure are all predictive of overall survival and adjusting for them influences the estimated hazard ratio of the treatment effect in favour of lenvatinib." (PMID 32265508, 2020). "In conclusion, our study proposed that the elevated serum ALT level is strongly associated with the abnormally elevated AFP level in patients with hepatitis B without developing HCC." (PMID 33490235, 2020). "Our analysis shows that the achievement of 3‐year survival time in patients with hepatitis B‐related HCC initially treated with TACE was associated with a higher BMI, lower AST, shorter APTT, lower AFP, antivirus treatment, smaller tumor size, solitary tumor, and the absence of vascular invasion." (PMID 31313476, 2019). "This reactivation of hepatitis B is usually accompanied by the deterioration of liver enzymes, indicating hepatocellular damage and regeneration, which may lead to AFP elevation." (PMID 31836006, 2019). "In multivariate analysis, through analysis of the clinical significance of the research data, alpha fetoprotein and hepatitis B virus infection were considered to be closely related with HCC, Therefore, we established three models to carry on the multivariate analysis." (PMID 29127353, 2017). "Seventy-three percent of the patients had compensated liver reserve function, and the primary etiology of HCC was viral hepatitis B or C. The median alpha fetoprotein (AFP) level was 46.6 ng/mL, and an AFP level ≥ 400 ng/mL was found in only 30.5% of the patients." (PMID 28957337, 2017). "In our study, the association of higher AFP ratios (> 1.0) with disease progression or recurrence was significant only in cases of HCC secondary to hepatitis B or non-viral causes, and this association was limited to patients who had normal ALT levels." (PMID 27304617, 2016). "This is an important limitation because patients with laboratory diagnosed hepatitis B or liver masses associated with a markedly elevated alpha-fetoprotein were generally unlikely to get a biopsy." (PMID 25668620, 2015). "However, a weak negative correlation occurs during pregnancy when the burden on the pregnant woman’s liver increases and hepatitis B virus infection may affect hepatocyte function, resulting in a relative decrease in AFP synthesis." (PMID 40256451, 2025). "Univariate analysis revealed statistically significant differences between the 2 groups regarding age, ALT, AST, GGT, AFP, STIP1, and hepatitis B virus infection (P < .05)." (PMID 38780206, 2024). "The etiology of hepatitis B HCC accounted for 94.5%, and 67.3% of patients had an alpha fetoprotein level > 200 ng/mL." (PMID 37393336, 2023).
hepatitis B (continued). "Age, gender, Child-Pugh class, hepatitis B virus (HBV) infection ratio, alpha fetoprotein (AFP) levels, albumin-bilirubin (ALBI) score, BCLC stage and ECOG-PS score were examined." (PMID 34988019, 2021). "The subgroups involved stratification by sex, alpha-fetoprotein (AFP; ≤400, >400), Eastern Cooperative Oncology Group (ECOG) performance status (PS), hepatitis B and C status, locoregional therapy, extrahepatic spread status, and portal vein thrombosis status." (PMID 33430312, 2021). "Concurrent testing of serum alpha-fetoprotein (AFP) intended for HCC screening (for chronic, but inactive hepatitis B virus infection) showed a very high value of 934.7 ng/mL (normal < 5 ng/mL)." (PMID 30208947, 2018). "AFP greater than 400 ng/mL, tumor size and hypersplenism were preoperative predictors of MVI in patients with solitary small hepatitis B related HCC." (PMID 24772137, 2014). "In this study, we report two cases of hepatitis B-related HCC that were persistently AFP-negative but showed a marked increase in serum AKR1B10 levels." (PMID 41907234, 2026). "Our analysis identified ten variables associated with a higher risk of mortality: older age, disease duration exceeding 5 years, frequency of ascites exceeding 5 episodes, concurrent hepatitis B, and elevated baseline levels of ALT, AST, DBil, ALP, ALB, and AFP." (PMID 40424464, 2025). "There was no history of hepatitis B infection, and the alpha-fetoprotein level was within normal limits." (PMID 40823067, 2025). "The present patient was admitted to our hospital with complaints of abdominal distension, with history of hepatitis B. Tumor markers, including alpha-fetoprotein, carcinoembryonic antigen, and CA 19-9, were within the normal range." (PMID 39640280, 2024). "Previous studies have demonstrated that specific laboratory parameters like alpha-fetoprotein (AFP) and its changes to treatment, inflammatory parameters like C-reactive protein, and etiological factors of HCC like hepatitis B or C have strong correlations with patient response to immunotherapy." (PMID 37598406, 2023). "Routine blood examination, biochemical tests, and analyses of alpha fetoprotein (AFP), carcinoembryonic antigen (CEA), cancer antigen 125 (CA125) and cancer antigen 19–9 (CA19–9), three systems of hepatitis B, hepatitis C antibody, HIV, RPR, and coagulation function were conducted." (PMID 32522174, 2020). "Univariate logistic regression analysis of baseline factors affecting ORR was performed for the following factors: Age, hepatitis B status, hepatitis C status, number of prior TACE procedures, ALBI grade, baseline α-fetoprotein (AFP) level, extrahepatic spread, and macrovascular invasion." (PMID 31284682, 2019). "The value of alpha-fetoprotein (AFP) in hepatitis B-related acute-on-chronic liver failure (HBACLF) is not fully understood." (PMID 29854714, 2018). "For instance, EA patients in REACH had a higher incidence of hepatitis B infection, macrovascular invasion, extrahepatic spread, Barcelona Clinic Liver Cancer stage C, increased concentration of AFP, and poorer ECOG PS than non-EA patients." (PMID 27776351, 2016). "Serology was negative for hepatitis B and hepatitis C. Levels of tumor markers alpha-fetoprotein (AFP), carcinoembryonic antigen (CEA), carbohydrate antigen 19-9 (CA 19-9) were normal." (PMID 26114004, 2015). "There were more patients with hepatitis B virus (HBV) infection among AFP non-responders than among AFP responders." (PMID 26252472, 2015). "The pathological mechanism of the good prognosis for NBNC-AFP(-)-HCC might be the negative expression of AFP in the absence of hepatitis B and C virus infections." (PMID 35293607, 2023). "The findings highlight the potential of regular AFP testing to enhance survival in HCC patients, especially those with hepatitis B. Integrating frequent AFP testing with ultrasonography could increase the likelihood of early detection and access to curative treatments." (PMID 38201578, 2023).
hepatitis B (continued). "The study suggests that combining AFP tests with ultrasound screenings could better detect HCC early, offering enhanced treatment opportunities and improved survival chances, especially for hepatitis B patients." (PMID 38201578, 2023). "In summary, when the patient's serum CA199 increased, AFP did not change significantly, and there was no previous history of hepatitis B. CT revealed a low-density mass in the liver, ring enhancement in the arterial phase, and heterogeneous enhancement of the tumor in the delayed phase." (PMID 35945590, 2022). "To evaluate the diagnostic values of serum MCP-1 and prolactin in distinguishing HCC patients from non-HCC hepatitis B carriers in comparison with serum AFP, we performed the ROC curve analysis to determine the sensitivity and specificity of these three markers in the SGH cohort." (PMID 23874805, 2013). "AFP levels were <20 ng/ml in all of these non-HCC hepatitis B carriers." (PMID 23874805, 2013). "However, there was no survival difference according to gender, age, control of HCC, liver function, levels of AFP, CEA and CA19-9, hepatitis virus B infection, intracranial hemorrhage, location and number of brain lesions, and interval between diagnosis of HCC and BM, in our patient group." (PMID 22292912, 2012). "AFP mRNA levels showed strong positive correlations with TUG1 and unfavorable prognosis in patients with non-hepatitis B/non-hepatitis C HCC (NBNC-HCC)." (PMID 31973032, 2020). "Initial laboratory evaluation revealed the presence of tuberculosis serum antibody, hepatitis B, hepatitis C, HIV infection and treponema pallidum antibody were negative and CEA, AFP, CA199 and IFN-γwere all within normal ranges." (PMID 29849940, 2018). "Serum alpha-fetoprotein (AFP) was normal, and serology for hepatitis B and C was negative." (PMID 39021472, 2024).
yolk sac tumor (132 papers, 2007 to 2026). A non-seminomatous malignant germ cell tumor composed of primitive germ cells. "The association between elevated AFP levels in yolk sac tumors at diagnosis and prognostic significance remains debated." (PMID 40037273, 2025). "Many cases also contain yolk sac tumor elements and are therefore associated with increased AFP levels in approximately 33–65% of patients." (PMID 40723200, 2025). "AFP: Elevated levels of AFP are often a hallmark of specific subtypes of ovarian germ cell tumors, primarily yolk sac tumors." (PMID 38380211, 2024). "The tumor marker associated with 60–90% of yolk sac tumors is alpha fetoprotein (α-FP), and its normalization with chemotherapy is regarded as an indication of complete clinical response to the treatment." (PMID 35204394, 2022). "Yolk-sac tumors are often associated with elevated AFP levels and are more aggressive tumors that often can metastasize within the perineum to the liver, lung or brain." (PMID 35937851, 2022). "An elevated serum AFP level is closely associated with yolk-sac tumors in more than 90% of children as the tumoral cells synthetize AFP." (PMID 35804952, 2022). "Some authors propose to call all these AFP-producing neoplasms associated with conventional carcinoma in various organs with the name of “somatically derived yolk sac tumor”." (PMID 34977100, 2021). "AFP is produced by endodermal sinus tumors, either alone or in association with other types of GCTs, and β-HCG is only produced by syncytiotrophoblasts, which are components of choriocarcinoma." (PMID 30885154, 2019). "An elevated serum AFP level is closely associated with yolk sac tumors in more than 90% of patients." (PMID 25547829, 2014). "Other rare elements encountered include neuroectodermal tissue, yolk sac tumor (associated with elevated alpha-fetoprotein), and melanocytic and neuroendocrine elements." (PMID 24716055, 2014). "The three sensitive diagnostic markers for yolk sac tumor are alpha-fetoprotein, glypican-3 and SALL4." (PMID 22978485, 2012). "Elevated serum AFP level is strongly associated with >90% of yolk-sac tumors, whereas immature teratomas may present a slightly elevated serum AFP level." (PMID 35804952, 2022). "Both of these tumors are hormone-producing: yolk sac tumors secrete AFP, while choriocarcinomas secrete beta-hCG." (PMID 41230344, 2025). "Combined with the immunohistochemical profile and significantly elevated serum AFP, these findings confirmed the diagnosis of primary anterior mediastinal yolk sac tumor." (PMID 41235014, 2025). "The authors cautioned against interpreting moderate AFP elevations as evidence of embryonal carcinoma or yolk sac tumour and warned against inappropriate interventions." (PMID 39934683, 2025). "Imaging findings, serum AFP level, and treatment of the pelvic yolk sac tumor in postpubertal patients." (PMID 41001168, 2025). "Given the patient’s age, tumor morphology, and markedly elevated AFP, a right ovarian yolk sac tumor was initially considered." (PMID 40919162, 2025). "Tumor markers such as AFP are significantly elevated in patients with yolk sac tumor and serve as a marker for the detection of the tumor, monitoring the treatment, and identifying the recurrence." (PMID 41001168, 2025). "In prepubertal patients, teratomas are generally benign, whereas yolk sac tumors typically show markedly elevated AFP and distinct histological features." (PMID 41255769, 2025). "In our study, pure yolk sac tumor histology was the most frequent pathological finding, and 80% of patients had elevated AFP levels at the initial diagnosis, which is in favor of the presence of a yolk sac or embryonal carcinoma component." (PMID 38892991, 2024). "Specific tumor markers like elevated alpha-fetoprotein indicate the presence of a yolk sac tumor, and elevated b-hCG indicates the presence of a germinoma or choriocarcinoma." (PMID 38993426, 2024).